CDH2 (cadherin 2)
Diseases named in the same sentence as CDH2 in open-access papers (continued):
Sharing a sentence is not in itself a finding about the gene and the disease.
lymph node metastasis (18 papers, 2003 to 2025). "Also, CDH2 positivity in IHC staining was correlated to lymph node metastasis of TNBC, but CDH1 was not." (PMID 28392805, 2017).
triple-negative breast carcinoma (15 papers, 2013 to 2025). An invasive breast carcinoma which is negative for expression of estrogen receptor (ER), progesterone receptor (PR), and human epidermal growth factor receptor 2 (HER2). "Its association with triple-negative breast cancer (TNBC) was first reported in 2015, as the phosphorylation of a large number of its substrates was identified to play a role in adhesion and migration of MDA-MB-231 cells and U2OS cells, such as IGFBP7 and cadherin-2 (CDH2)." (PMID 34988120, 2021).
meningioma (14 papers, 2012 to 2024). A generally slow growing tumor attached to the dura mater. "This research has showed that genes that are involved in cadherin switch, CDH1 and CDH2, play a role in meningioma progression." (PMID 33915799, 2021). "We found that repression of CDH2 blocked meningioma tumorigenesis, and moreover, that both genetic and pharmacologic inhibition of CDH2 with ADH-1 attenuated meningioma cell proliferation in coculture with human cerebral organoids." (PMID 32968068, 2020). "Genetic changes of CDH1 and CDH2 are present in all meningioma grades." (PMID 33915799, 2021). "We showed that genes involved in cadherin switch, CDH1 and CDH2, may play a role in the development and progression of meningiomas, where both genes are involved and the basis for defective EMT has been established." (PMID 33915799, 2021). "To determine if inhibition of CDH2 blocked meningioma tumorigenesis, we cocultured M10GdCas9-KRAB cells, transduced with either sgNTC or sgCDH2, with human cerebral organoids, and monitored meningioma cell interactions in the tumor microenvironment using live imaging." (PMID 32968068, 2020). "Therefore, we can speculate that CDH1 and CDH2 genes may represent a useful prognostic marker of meningioma progression, especially since genetic changes occur in benign stages and increase their frequency by transitioning to malignant forms (especially LOH in the CDH2 gene)." (PMID 33915799, 2021). "A minority of meningioma cells in 2D culture expressed genes enriched in regions with elevated ADC, such as CDH2 and PTPRZ1." (PMID 32968068, 2020). "Among these genes, we find that FOXM1, CDH2, and PTPRZ1 are heterogeneously expressed in individual meningiomas." (PMID 32968068, 2020). "High ADC regions in meningiomas correlate with areas overexpressing the CDH2 and PTPRZ1 genes, which drive meningioma tumorigenesis and may represent novel therapeutic targets." (PMID 36497370, 2022). "To understand the function of these genes in meningioma, we develop a human cerebral organoid model of meningioma and validate the high ADC marker genes CDH2 and PTPRZ1 as potential targets for meningioma therapy using live imaging, single cell RNA sequencing, CRISPR interference, and pharmacology." (PMID 32968068, 2020). "There was also a meningioma cell cluster enriched for CDH2 and PTPRZ1 that was present after 12 h in 3D monoculture, but not after 14 days, suggesting that neither 2D nor 3D monoculture conditions accurately recapitulate the in vivo molecular heterogeneity of meningioma cells." (PMID 32968068, 2020). "We performed immunofluorescence for Ki-67 and found that repression of CDH2 and PTPRZ1 each attenuated meningioma cell proliferation compared to cells transfected with non-targeting sgRNAs (sgNTC)." (PMID 32968068, 2020).
multiple myeloma (14 papers, 2015 to 2025). "It is also known as cadherin 2 because of the increase in cadherin 2 gene expression in multiple myeloma patients for whom N-cadherin is held responsible." (PMID 36572878, 2022). "Additionally, CDH2 enhances the activity of nuclear β-catenin-mediated drug resistance in myeloma." (PMID 39199357, 2024). "We selected genes (PHOX2A, CDH2, and HTATIP2) whose methylation levels significantly changed to validate their expression via qRT‒PCR in CD138+ myeloma cells." (PMID 41146049, 2025).
leukemia (13 papers, 2012 to 2025). A malignant (clonal) hematologic disorder, involving hematopoietic stem cells and characterized by the presence of primitive or atypical myeloid or lymphoid cells in the bone marrow and the blood. "CDH2 knockdown in iMSC reduce their ability to support the proliferation of patient-derived leukemia samples, three diagnostic and one relapse samples." (PMID 35977468, 2022). "This study demonstrated that knockdown of CDH2 in leukaemia cells reduce their proliferation while increasing sensitivity to dexamethasone treatment (Refs 3, 4)." (PMID 37132370, 2023). "Heterologous contact of the leukemia cells in these co-culture conditions induces upregulated expression of CDH2, and knockdown of CDH2 in iMSC increases the sensitivity of patient-derived blasts." (PMID 35977468, 2022). "develop a synthetic human bone marrow milieu and identify that CDH2 mediates niche-dependent leukemia proliferation and treatment resistance." (PMID 35977468, 2022). "Small hairpin RNA (shRNA) CDH2 knockdown in four different leukemia cell lines result in reduced proliferation in niche-free suspension cultures." (PMID 35977468, 2022). "We find consistent upregulation of cell adhesion molecule CDH2 in i-niche primed blasts across two patient leukemia samples." (PMID 35977468, 2022). "Taken together, these data reveal a means of clinically targeting niche-mediated leukemia treatment resistance using the CDH2 antagonist ADH-1." (PMID 35977468, 2022). "In summary, these data show that BM-iPSC derived niche cell types support leukemia cells, and leukemia blasts primed by the i-niche cells upregulate CDH2 expression." (PMID 35977468, 2022). "We find that CDH2 knockdown leukemia cells, co-cultured under modified culture conditions to facilitate niche dependence, fail to survive on iMSC cells and show reduced proliferation on iANG." (PMID 35977468, 2022). "The overexpression of CDH2 observed in T-cell Leukemia samples analyzed in our study and its role as a hub protein indicates that this gene needs to be investigated further using experimental procedures to assess its significance in Leukemogenesis." (PMID 24688641, 2012). "Finally, we review emerging therapeutic approaches that directly target CDH2-mediated adhesive interactions between the BM cells and leukaemia cells." (PMID 37132370, 2023). "CDH2 is upregulated upon heterologous cell contact of the leukemic cells with iMSC; in contrast, CDH2 knockdown in either leukemia blasts or iMSC disrupts this interaction, impairs blast survival and proliferation, and leads to the downregulation of key oncogenic pathways (e.g., JAK/STAT signaling)." (PMID 35977468, 2022). "Consequently, we test CDH2 antagonist ADH-1 (previously in Phase I/II trials for solid tumors) in a very aggressive patient-derived xenograft leukemia mouse model." (PMID 35977468, 2022). "In keeping with these studies, recent research shows upregulation of CDH2, a known marker of EMT, in niche-primed leukaemia cells." (PMID 37132370, 2023). "They show that CDH2 is targetable in vivo via ADH-1, which shows high efficacy and low toxicity in a very aggressive leukemia PDX model." (PMID 35977468, 2022). "In conclusion, CDH2 is an important molecule in both the healthy and malignant BM microenvironment, supporting both non-malignant haematopoietic cells and leukaemia cells." (PMID 37132370, 2023). "Loss of normal hematopoiesis is a classical event during human myeloproliferative neoplasias and leukemias where the niche downregulate essential HSPC retention factors as CXCL12, SCF, LepR, Angpt1, Cdh2, Slit2, and TGF-β1 though pro-inflammatory factors secreted by leukemia-initiating cells." (PMID 28111575, 2016).
neuroblastoma (13 papers, 2005 to 2022). Neuroblastoma (NB) is the most common solid, extracranial childhood tumor. "Neuroblastoma-specific mesenchymal transcriptional signature was also repressed after BAF disruption in neuroblastoma cells, involving the epigenetic repression of key regulators of the mesenchymal phenotype, such as SNAI2, CDH11, CDH2, LOXL2 and NOTCH2." (PMID 36057593, 2022).
metastatic carcinoma (12 papers, 2008 to 2024). A carcinoma which has spread from the original site of growth to another anatomic site. "Therefore, in the observed tissues, SPARCL1 was most highly expressed in normal colorectal tissues, and CDH2 had the highest expression in normal liver tissues and liver metastatic cancer tissues, while CP, HP, TF, and SERPINA5 with the most highly expressed in normal liver tissues." (PMID 34422629, 2021). "We also observed CDH2, CP, HP, TF, and SERPINA5 were upregulated in liver metastatic cancer tissues and downregulated in primary cancer tissues; whereas SPARCL1 exhibited the opposite expression pattern." (PMID 34422629, 2021).
diabetes (11 papers, 2017 to 2023). "Compared to patients without diabetes, patients with T2D showed a decreased E-cadherin/N-cadherin (CDH1/CDH2) ratio in prostate tissue, indicating a switch of epithelial-mesenchymal transition (EMT), which is a pivotal process in carcinogenesis." (PMID 33207809, 2020). "There were 8 differentially methylated genes (CDH2/PCDHB10/PCDHB11/PCDHB14/PCDHB16/PCDHB3/PCDHB6/PCDHB9) in the LAA subgroup and 1 (CDH2) in the SVD subgroup after adjusting for smoking, drinking, history of hypertension and diabetes, and blood lipid levels (p < 0.05)." (PMID 35480311, 2022). "Here we observed a decreased CDH1/CDH2 ratio in PCa samples of patients with T2D suggesting that EMT is induced in these samples, which may contribute to the more aggressive PCa phenotype of patients with diabetes." (PMID 33207809, 2020).
asthma (10 papers, 2021 to 2026). "CDH2 encodes for N-cadherin, which is a transmembrane protein known to have reduced expression in the airway epithelium of patients with asthma." (PMID 33923870, 2021).
cardiomyopathies (10 papers, 2016 to 2025). "In contrast, the CDH2-specific pool was enriched for a variety of cardiomyopathies." (PMID 30630894, 2019). "Furthermore, CDH2 was also identified as a candidate gene involved in cardiomyopathy." (PMID 32993537, 2020).
malignant glioma (10 papers, 2010 to 2022). A grade III or grade IV glioma arising from the central nervous system. "EMT, as a key factor of malignant glioma invasion enhancement, can be characterized by an increase in the expression of biomarkers, such as CDH2, VIM, FN1, SNAI1, SNAI2, ACTA2, and so on." (PMID 34034744, 2021).
dilated cardiomyopathy (9 papers, 2010 to 2025). "In mice, loss of AJ proteins in the heart – N-cadherin (CDH2), β-catenin, αE-catenin or αT-catenin (CTNNA3) – causes dilated cardiomyopathy." (PMID 30630894, 2019). "Multiple studies showed that cadherin-2 (Cdh2) increased in dilated cardiomyopathies." (PMID 32960902, 2020). "For example, mutations in JUP, DSP, PKP2, DSG2, DSC2, CTNNA3, CDH2, or PLN (all of them more abundant in LV) predominantly lead to arrhythmogenic right ventricular cardiomyopathy, and mutations in MYH7, HSPB7, NEXN and MYPN (also all more abundant in LV) lead to dilated cardiomyopathy." (PMID 32291283, 2020).
breast invasive carcinoma (8 papers, 2014 to 2024). "Actually, simultaneous deregulation of miR200cand miR-30c could significantly reduce the survivalrate of breast invasive carcinoma cells via up-regulationof OCT4, SOX2, c-MYC, SNAI1, ZEB1, CDH2 and down-regulation of CDH1 (P=0.02)." (PMID 31376329, 2020). "Actually, deregulation of miR‐204, miR‐200c, miR‐34a, and miR‐10b simultaneously could significantly reduce the survival rate of breast invasive carcinoma via up‐regulation of OCT4, SOX2, KLF4, c‐MYC, NOTCH1, SNAI1, ZEB1, and CDH2 and down‐regulation of CDH1." (PMID 30710426, 2019).
prostate tumor (8 papers, 2015 to 2024). "In particular, we found primarily overexpression of CTNNB1, CDH1, SMAD2, SMAD3, TCF3, LEF1 in younger patients and overexpression of SNAI1 and underexpression of KRT5, KRT19, OCLN, CDH2 and MUC1 which clearly indicates different characteristics of prostate tumor in younger vs older patients." (PMID 29206234, 2017).
sarcoma (8 papers, 2012 to 2022). A usually aggressive malignant neoplasm of the soft tissue or bone. "Calpain-6 may also regulate the Hippo pathway and YAP transcriptional activity by modulating cell-cell interactions in sarcoma SCs because the suppression of calpain-6 with shRNA affected the expression of different genes coding cadherins such as CDH2 and CDH11." (PMID 36153320, 2022). "We selected CCND1, MTA1, STEAP1, CDH2, CDH11, and CDT2 genes that are known to be involved in metastatic spread in several sarcoma subtypes, and their abnormal expression in tumors correlates specifically with poor prognosis in ES patients." (PMID 25008066, 2014). "Moreover, the expression of CDH1 (E-cadherin) decreased, and the expression of CDH2 (N-cadherin) and VIM (vimentin) increased in the dECM compared to 2D culture with plastic dishes and culture on Matrigel, which is a crude extract of the basement membrane formed by Engelbreth-Holm-Swarm sarcomas." (PMID 31013621, 2019).
astrocytoma (7 papers, 1995 to 2025). "The genes CDH2, DDB2, DSP, EPO, FGF2, and TEK were overexpressed in an astrocytoma cell line." (PMID 36142793, 2022).
esophageal squamous cell carcinoma (7 papers, 2015 to 2024). Esophageal squamous cell carcinoma (ESCC) is a type of esophageal carcinoma (EC) that can affect any part of the esophagus, but is usually located in the upper or middle third. "The roles of CDH2 have been demonstrated in several cancers such as increasing invasiveness in melanoma cancer and esophageal squamous cell carcinomas." (PMID 39199357, 2024).
Alzheimer disease (6 papers, 2014 to 2022). A progressive, neurodegenerative disease characterized by loss of function and death of nerve cells in several areas of the brain leading to loss of cognitive function such as memory and language. "A change in the potential to bind the transcription factor (C/EBPβ) was found for the derived CDH2 sequence, similar to an inferred change in predicted transcription factor DNA-binding in Alzheimer's disease, which is also associated with OCD." (PMID 25303325, 2014).
cyst (6 papers, 2011 to 2024). A sac-like closed membranous structure that may be empty or contain fluid or amorphous material. "Two proteins involved with cell–cell adhesion were found in cyst proteome and were missing from control samples: cadherin 2 and claudin I, of adherens junction and tight junction, respectively." (PMID 38891869, 2024). "Up-regulation of CDH2 is a hallmark of EMT, which has been described extensively for cyst-lining cells 67,68." (PMID 34301992, 2021).
laryngeal carcinoma (6 papers, 2019 to 2023). Carcinoma that arises from the laryngeal epithelium. "In laryngeal carcinoma, PRMT5 regulates WNT4 expression, and PRMT5–WNT4 activates β-catenin to induce cadherin 2 (CDH2: also known as N-cadherin) and SNAIL expression, which is involved in EMT and promotes cell migration and lymph-node metastasis." (PMID 36980950, 2023).
thyroid (6 papers, 2017 to 2025). "N-cadherin (encoded by CDH2) and vimentin (encoded by VIM) were identified to promote thyroid tumorigenesis." (PMID 32033410, 2020).
arrhythmogenic right ventricular cardiomyopathy (5 papers, 2015 to 2023). "Variants of CDH2 also cause arrhythmogenic right ventricular cardiomyopathy (ARVC), Peters anomaly, and brain arteriovenous malformation in a few cases." (PMID 36111109, 2022). "Deficiency of CDH2 is associated with arrhythmogenic right ventricular cardiomyopathy (OMIM: 618920) and agenesis of the corpus callosum, cardiac, ocular, and genital syndrome (OMIM: 618929)." (PMID 36111109, 2022). "Mutations in CDH2 has been widely studied in arrhythmogenic right ventricular cardiomyopathy (ARVC), but the effects of APA of Cdh2 have not been reported and worth further study." (PMID 36741323, 2023).
autism (5 papers, 2012 to 2024). Persistent deficits in social interaction and communication and interaction as well as a markedly restricted repertoire of activity and interest as well as repetitive patterns of behavior. "The first genetic evidence associated flank sucking in Dobermans with the CDH2 locus, a gene which has also been associated with autism in humans." (PMID 22844513, 2012). "Studies in humans have found six de novo CDH2 missense mutations in EC5 associated with a variety of neurodevelopmental disorders, ranging from subtle disruptions of craniofacial morphogenesis and attention deficit to severe autistic disorders and intellectual disabilities." (PMID 39570883, 2024).
depression (5 papers, 2011 to 2024). "Within the “depression” group, we have identified a notably higher frequency of the genetic variant rs17445840-T in the CDH2 gene." (PMID 38699454, 2024).
epilepsy (5 papers, 2014 to 2025). A brain disorder characterized by episodes of abnormally increased neuronal discharge resulting in transient episodes of sensory or motor neurological dysfunction, or psychic dysfunction. "This suggests that epilepsy may not always be present in patients with CDH2 haploinsufficiency, as we observed in one of our four patients." (PMID 24834135, 2014).
gallbladder cancer (5 papers, 2020 to 2024). "In gallbladder cancer, CDH2 is not only closely related to a poor prognosis, but also to clinicopathological features such as tumor size, invasion, and lymph node metastasis." (PMID 34880371, 2021).
cervical squamous cell carcinoma (4 papers, 2016 to 2025). A squamous cell carcinoma arising from the cervical epithelium. "As per the survival analysis in cervical squamous cell carcinoma (CESC), CDH2 (N-cadherin) shows a significant overall survival association with a p-value of 0.0017 and a hazard ratio (HR) of 2.1, indicating its strong prognostic relevance in disease progression." (PMID 41266827, 2025).
clear cell renal cell carcinoma (4 papers, 2020 to 2024). "We aimed to determine prognostic value of six key EMT markers (CDH1, CDH2, SNAI1, SNAI2, VIM, TWIST1) in clear cell renal cell carcinoma (ccRCC)." (PMID 31915310, 2020).
diabetic nephropathy (4 papers, 2022 to 2025). "In addition to our evidence on plasma samples from Prader-Willi syndrome, increased circulating plasma levels of CDH2 have been associated with diabetic nephropathy, and malignant bone and soft tissue tumors." (PMID 39017916, 2025).
head and neck cancer (4 papers, 2018 to 2025). A primary or metastatic malignant neoplasm affecting the head and neck. "Among them, 6 genes were highly expressed in head and neck cancers, namely SLC1A5, ETS1, NDRG1, RHEB, HIF1A and CDH2." (PMID 41317550, 2025).
Hyperglycemia (4 papers, 2016 to 2024). An increased concentration of glucose in the blood. "The initiation of EMT in HaCaT cells from hyperglycemia was confirmed by a morphological change, the increased expression of CDH2, KRT10, and ACTA2, and the downregulation of CDH1." (PMID 36827547, 2023).
ischemia (4 papers, 2015 to 2022). A hypoperfusion of the BLOOD through an organ or tissue caused by a PATHOLOGIC CONSTRICTION or obstruction of its BLOOD VESSELS, or an absence of BLOOD CIRCULATION. "Under nonischemic conditions, pericytes expressed Cdh19, Cdh6, Cdh10, Cdh4, Cdh13, and Cdh5; after ischemia, the cadherin genes that were predominantly expressed were Cdh15, Cdh11, Cdh3, and Cdh2." (PMID 33726849, 2021). "Four hours after ischemia onset, neocortical mRNA levels of all analyzed genes except VE-cadherin (Cdh5) were significantly down-regulated by about 50%, whereat the fold change ranged between 0.55 for α-catenin 2 (Ctnna2) and 0.38 for N-cadherin (Cdh2)." (PMID 31089963, 2019). "A loss of the neuronal adherence junction molecule N-cadherin (Cdh2) due to ischemia, as might be interpreted from the measured diminished Cdh2 mRNA level, can cause neuroepithelial and thereby structural damage." (PMID 31089963, 2019).